ST3GAL5 (ST3 beta-galactoside alpha-2,3-sialyltransferase 5)
Diseases named in the same sentence as ST3GAL5 in open-access papers (continued):
Sharing a sentence is not in itself a finding about the gene and the disease.
Epileptic encephalopathy (1 paper, 2023). A condition in which epileptiform abnormalities are believed to contribute to the progressive disturbance in cerebral function. "Biallelic ST3GAL5 loss-of-function variants result in systemic ganglioside deficiency, an infantile-onset neurodevelopmental syndrome characterized by intractable epileptic encephalopathy, auditory and visual impairment, global psychomotor delay, extrapyramidal movements, and untimely death." (PMID 37014712, 2023). "Humans with severe, biallelic loss-of-function mutations in ST3GAL5 exhibit complete absence of GM3 and its downstream derivatives in plasma and, presumably, brain tissue, and present with epileptic encephalopathy and psychomotor stagnation within a few months of life." (PMID 37014712, 2023).
meningioma (1 paper, 2021). A generally slow growing tumor attached to the dura mater. "The decreased expression of ST3GAL5 after glycation results in a decreasing expression of GM3 in benign meningioma cells." (PMID 34943806, 2021). "Glycation of meningioma cell lines resulted in decreased ST3GAL5 expression in both cell lines." (PMID 34943806, 2021).
Sepsis (1 paper, 2025). Sepsis is defined as life-threatening organ dysfunction caused by a dysregulated host response to infection. "The key genes distinguishing sepsis from healthy conditions include B3GNT5, FUT11, ST3GAL5, MAN1C1, C1GALT1C1, and GALNT14." (PMID 39981259, 2025). "The expression trends of six Golgi-related genes (B3GNT5, FUT11, ST3GAL5, MAN1C1, C1GALT1C1, and GALNT14) aligned with the patterns observed in the hub genes from the initial sepsis dataset analysis." (PMID 39981259, 2025).
tumor (21 papers, 2012 to 2025). "ST3Gal5, also named GM3 synthase, is differentially expressed in multiple tumor types compared to adjacent healthy tissue, and associated with beneficial or poor prognosis, depending on the type of tumor." (PMID 37266839, 2023). "Previous studies have reported that PLA2G2D and ST3GAL5 may be potential tumor biomarkers associated with immune cells." (PMID 37205993, 2023). "The violin plots demonstrate that genes including CTNV, FIB, GAB2, LAMP3, ST3GAL1 and ST3GAL5 exhibit distinct expression profiles, with tumour tissues showing markedly different expression distributions compared to normal controls." (PMID 41362116, 2025). "The expression levels of ST3Gal5 during malignancy, and also relative to the corresponding normal tissue, vary depending on the tumor type." (PMID 38785323, 2024). "Several studies have shown the relevance of ST3Gal5 in regulating migration and invasion of tumor cells." (PMID 38785323, 2024). "To evaluate overall ST3Gal5 levels in the established MC38 and CT26 tumors, we checked the gene expression of ST3Gal5 on frozen tumor tissues with qRT-PCR." (PMID 38785323, 2024). "In conclusion, we demonstrate that the contribution of only ST3Gal5 on anti-tumor immunity is modest." (PMID 38785323, 2024). "Gene Ontology and Kyoto Encyclopedia of Genes and Genomes pathway enrichment analyses indicated the involvement of ST3GAL5 in tumor immunoregulation." (PMID 36172374, 2022). "Therefore, in this paper we evaluated the role of ST3Gal5 in regulating the anti-tumor immune response in CRC." (PMID 38785323, 2024). "Nevertheless, how ST3Gal5, and as a consequence the generation of GSLs, affects tumor immunogenicity still remains unclear." (PMID 38785323, 2024). "Besides, we show that knocking out ST3Gal5 in CT26 tumors results in an increase of Tregs in the TME with limited impact on tumor growth in vivo." (PMID 38785323, 2024). "To investigate the role of ST3Gal5 in tumor immunogenicity, we knocked out the ST3Gal5 gene in two different murine CRC cell lines: MC38 and CT26; both of them having comparable expression of ST3Gal5 We designed two different CRISPR/Cas9 gRNAs, targeting distinct regions in the ST3Gal5 gene." (PMID 38785323, 2024). "Similarly, downregulated genes identified in Cluster 1 have been previously associated with more aggressive tumor characteristics and higher tumor grade; these include RNF39, ADAMTS8, SLC25A42, ST3GAL5, and ZBED3." (PMID 39766155, 2024). "However, only 5 of the 10 mice developed a tumor in the MC38-MOCK group suggesting a low tumor take compared to the ST3Gal5 KO group." (PMID 38785323, 2024). "Therefore, to gain more insight into the TME of MC38 and CT26 tumors and its relation with ST3Gal5 expression, we evaluated the immune cell composition in frozen tumor tissues and tumor cell suspensions." (PMID 38785323, 2024). "The involvement of ST3GAL5 in tumor immunomodulation was thus indicated." (PMID 36172374, 2022). "Notably, among the 5-gene signature, only the gene HLF is involved in tumor immunity and the gene ST3GAL5 is involved in tumor invasion, migration, and proliferation." (PMID 31998783, 2020). "Therefore, we postulate that the effect of ST3Gal5 on anti-tumor immunity could be tumor type-dependent, since the composition of gangliosides as well as how they modulate the immune response could be different among cancer types." (PMID 38785323, 2024). "Intriguingly, we did not detect any differences between the MOCK and ST3Gal5 samples, indicating that other cell types, such as fibroblasts and endothelial cells within the TME still harbor significant ST3Gal5 which may explain the similarity in tumor growth in vivo." (PMID 38785323, 2024). "Strikingly, CD4+ T cells and CD4+ Tregs were significantly increased in ST3Gal5 KO tumors, while percentages of CD8+ T cells and NK cells remained similar in both tumor types." (PMID 38785323, 2024).
tumor (continued). "In GSE73731 dataset (n = 256 in total), upregulated ST3GAL5 (p < 0.0001) and ST3GAL6 (p = 0.0099) was positively correlated only with tumor grade in ccRCC, respectively." (PMID 36172374, 2022). "Our study further revealed that ST3GAL5 overexpression in ccRCC is significantly associated with immune infiltration (including CD8+ T cells, macrophages and B cells) and CD8+ T cell exhaustion, suggesting its overexpression may influence tumor immune microenvironment." (PMID 36172374, 2022). "Then, in UALCAN database, we found JUP and ITGB4 were higher expressed in tumor while ST3GAL5 and ST8SIA1 were lower expressed in tumor." (PMID 34402716, 2021). "Meanwhile, the GEPIA database showed that JUP, ITGB4, ST3GAL2, ST3GAL5 and B4GALNT1 were higher expressed in tumor samples than in paired normal tissues." (PMID 34402716, 2021). "Although knocking out ST3Gal5 in both cell lines did not affect in vivo tumor growth, we observed enhanced levels of regulatory T cells in CT26 tumors lacking ST3Gal5." (PMID 38785323, 2024). "Nevertheless, the increase in Tregs in ST3Gal5 KO tumors did not impact tumor growth in our CRC mouse model." (PMID 38785323, 2024). "Similarly, deletion of LCS (B4GALT5), or GM3 synthase (ST3GAL5) markedly reduced the growth of MIA PaCa-2 xenografts, as evident by reductions in tumor weight and size." (PMID 36709325, 2023). "Taken together, in future it is necessary to characterize the roles of ST3GAL5 in cancer cells and nonmalignant cells in the tumor stroma during ccRCC development." (PMID 36172374, 2022). "Tumor cells highly expressed donor synthesis genes (NANS, CMAS, and the transporter SLC35A1), while the stroma showed enriched expression of sialyltransferases involved in α2-3, α2-6 and α2-8 sialylation (ST3GAL2, ST3GAL5, ST6GAL2, ST6GALNAC5, ST6GALNAC6, ST8SIA1 and ST8SIA2)." (PMID 38594506, 2024). "Our ST3Gal5 KO tumor cell lines do not have sialylated GSLs, but they still express α2-3 Sias carried on glycoproteins, suggesting that the modulation of the anti-tumor immune response in CRC is more likely mediated by sialylation on proteins rather than sialylated GSLs." (PMID 38785323, 2024). "However, in line with the in vivo tumor growth data, we did not observe any significant differences in CD8+ T cell infiltration in MC38 and CT26 tumors with ST3Gal5-deficiency compared to the MOCK control tumors." (PMID 38785323, 2024). "In summary, we have demonstrated that we could specifically ablate sialylated glycolipids by knocking out ST3Gal5 in two murine cell lines, however this did not impact tumor growth in vivo." (PMID 38785323, 2024). "The expression level of gangliosides in different tissues and tumor types mainly depends on the level of expression of glycosyltransferases involved in their biosynthesis, such as the ST3 β-galactoside α2-3 sialyltransferase 5 (ST3Gal5) which is the enzyme generating monosialylated gangliosides." (PMID 37266839, 2023). "Thus, fibroblasts, stroma, blood vessels and other immune cells in the TME, are still sialylated and therefore, might compensate for the lack of ST3Gal5 from tumor cells." (PMID 38785323, 2024). "Considering the infiltrating immune cells in the tumor areas, we could not entirely exclude the contribution of the ST3GAL5 expression in non-tumor cells to the conclusion on its overexpression in the ccRCCs by the transcriptomic data in TCGA-BLCA and GEO datasets alone." (PMID 36172374, 2022). "Even though Treg levels were more elevated in ST3Gal5 KO tumors, suggestive of a more immunosuppressive TME, this was not sufficient to affect the tumor growth." (PMID 38785323, 2024).
tumor (continued). "The RT-qPCR analysis showed that PLCE1, ST8SIA1, ST3GAL5, and GBA2 were aberrantly regulated between the tumor and nontumor cell lines, while the results of PTGS1 and AMT showed no significance." (PMID 38454278, 2024). "Blocking ST3GAL5 and probably ST8SIA1/3 could allow LacCer accumulation while preventing the formation of GM3 and GD3, thereby disarming tumor-driven immunosuppression without depriving immune cells of essential lipids." (PMID 40903462, 2025).
cancer (17 papers, 2008 to 2025). A tumor composed of atypical neoplastic, often pleomorphic cells that invade other tissues. "In addition to CD8+ T cells, the infiltrating macrophages and B cells inside tumors were also significantly associated with ST3GAL5 levels in cancer cells." (PMID 36172374, 2022). "In cancer, the expression levels of ST3Gal5 are altered, potentially leading to a different composition of sialylated GSLs within the TME." (PMID 38785323, 2024). "Concordant with elevated GM3 levels in KRAS mutant cell lines, high-level expression of ST3GAL5, which encodes GM3S, correlated with shortened survival time in KRAS mutant cancers." (PMID 36709325, 2023). "The fact that inhibition of GM3 synthase led to anti-cancer effects in MB, and GM3 was found abundantly in MB, renders the ST3GAL5 gene a desirable target for MB treatment." (PMID 36677837, 2023). "Overall, the role of ST3GAL5 in carcinogenesis is cancer-type dependent." (PMID 36172374, 2022). "In addition, strong signals for ST3GAL5, CD8 and PD-1 were detected in cancer regions, while very weak and few positive signals for ST3GAL5, CD8 and PD-1 were observed in the adjacent normal kidney regions on the same field." (PMID 36172374, 2022). "In addition, abnormal expression of ST3Gal5 is found in multiple types of cancers." (PMID 38785323, 2024). "In the CCLE database, expression of JUP, ITGB4, ST8SIA5, ST8SIA1, ST3GAL2, ST3GAL5 and B4GALNT1 in pan-cancer were explored." (PMID 34402716, 2021). "We have conducted an integrated analysis of genomic, epigenomic, and transcriptomic data to estimate how the key SA genes, namely CMAS, ST3GAL1, ST3GAL5, and NEU1, are regulated across different cancer types." (PMID 32296639, 2020).
infection (5 papers, 2016 to 2025). The state of being infected such as from the introduction of a foreign agent such as serum, vaccine, antigenic substance or organism. "Transfection of HEKΔSiaGSL cells with ST3Gal5, known as sialyllactosyl-ceramide (GM3) synthase, results in ∼2.5-fold enhanced HU02Av−H5 infection but, intriguingly, infection was more efficiently enhanced by ST3Gal5 in HEKΔSia (∼6-fold) and HEKΔSiaN (∼15-fold) cells." (PMID 40487452, 2025). "In addition, infection with both strains modulated the expression of ST3Gal5 and ST8Sia5." (PMID 37515094, 2023).
metabolic disease (3 papers, 2015 to 2025). A congenital disorder (due to inherited enzyme abnormality) or acquired (due to failure of a metabolically important organ) disorder resulting from an abnormal metabolic process. "Ganglioside GM3 synthase (also called lactosylceramide alpha-2,3-sialyltransferase) deficiency (OMIM 609056) is caused by a mutation in the ST3GAL5 gene and is a rare metabolic disorder inherited as an autosomal recessive trait." (PMID 29342918, 2018). "Further, we have shown that expression of ganglioside GM3, which is the simplest ganglioside species synthesized by GM3 synthase (GM3S; also called SAT-I/ST3Gal-5), is increased in metabolic diseases." (PMID 26102277, 2015). "ST3GAL5 (GM3 synthase) catalyzes the synthesis of GM3 ganglioside, which is key to regulating insulin sensitivity and inflammation in metabolic diseases." (PMID 41301440, 2025).
movement disorder (1 paper, 2023). Neurological conditions resulting in abnormal voluntary or involuntary movement, which may impact the speed, fluency, quality and ease of movement. "We show in the present study that is indeed the case for St3gal5+/− heterozygous (HT) mice whose movement disorder and short‐term spatial memory loss are also corrected by GM1 administration." (PMID 37401916, 2023).
ST3GAL5 also shares sentences with these, for which no sentence is quoted: colon carcinoma (3 papers); infantile epilepsy (3); lung carcinoma (3); acute leukemia (2); diabetes (2); epidermoid carcinoma (2); Failure to thrive (2); lysosomal disorders (2); microcephaly (2); multiple myeloma (2); multiple sclerosis (2); Obesity (2); osteoarthritis (2); renal cell carcinoma (2); Arthritis (1); atherosclerosis (1); breast tumor (1); chronic myelogenous leukemia (1); clear cell renal cell carcinoma (1); cryptococcosis (1); Developmental stagnation (1); genetic disorder (1); glioma (1); glomerulosclerosis (1); hereditary spastic paraplegia (1); kidney disease (1); Lewis lung carcinoma (1); lung adenocarcinoma (1); lung squamous cell carcinoma (1); metabolic syndrome (1).
A further 9 diseases each share a sentence with ST3GAL5 in 1 paper.